SNORD116-3 (small nucleolar RNA, C/D box 116-3)
Synonyms: HBII-85-3
Gene: Small nucleolar RNA gene on chromosome 15 (25,056,860 to 25,056,954, forward strand). Ensembl gene ENSG00000207014.
Gene Ontology:
Biological process: RNA processing
Cellular component: nucleolus
Homologues: Orthologues: chimpanzee SNORD116 (100% identical), macaque SNORD116 (98% identical), rabbit SNORD116 (91% identical), rabbit SNORD116 (89% identical), rabbit SNORD116 (88% identical), rabbit SNORD116 (87% identical), rabbit SNORD116 (84% identical), rabbit SNORD116 (79% identical), rabbit SNORD116 (77% identical), rabbit SNORD116 (76% identical). Paralogues in human: SNORD116-9 (100% identical), SNORD116-5 (99% identical), SNORD116-7 (99% identical), SNORD116-8 (98% identical), SNORD116-1 (97% identical), SNORD116-4 (97% identical), SNORD116-2 (96% identical), SNORD116-6 (95% identical), SNORD116-14 (87% identical), SNORD116-17 (86% identical), SNORD116-19 (86% identical), SNORD116-15 (85% identical), and 20 more.